IL15RA (interleukin 15 receptor subunit alpha)
Diseases named in the same sentence as IL15RA in open-access papers (continued):
Sharing a sentence is not in itself a finding about the gene and the disease.
cancer (34 papers, 2009 to 2025). A tumor composed of atypical neoplastic, often pleomorphic cells that invade other tissues. "After binding with its ligand IL15, IL15RA expressed by malignant tumor cells presents it to NK and T cells, activating effector cells and further attacking malignant tumor cells [28‒31]." (PMID 39396119, 2024). "Provision of IL-15 within the TME likely involves CCR7+ DCs, which express high levels of IL-15 and IL-15RA, co-localize with NK cells in human cancers and can support further molecular interactions such as PVR:TIGIT55,71,72." (PMID 38267402, 2024). "Genetically engineered cells co-expressing IL-15/IL-15Rα complex for secretion is also emerging for cancer treatment." (PMID 38368374, 2024). "SOT101 is a superagonist fusion protein of interleukin (IL)-15 and the IL-15 receptor α (IL-15Rα) sushi+ domain, representing a promising clinical candidate for the treatment of cancer." (PMID 36300122, 2022). "In this study, we introduced a new gene delivery strategy using BV to transfer and express the IL-15 and IL-15Rα genes in murine cancer cells as well as to facilitate the intracellular assembly of proteins encoded by those genes." (PMID 34439192, 2021). "Using this method, we prepared a BacMam-based IL-15:IL-15Rα-secreting cell-based cancer vaccine which triggered a robust antitumor immune response in mice and, of particular note, induced cytotoxic CD8+ T cell activation." (PMID 34439192, 2021). "Both lentivirus and adenovirus systems have been used to make IL-15:IL-15Rα cell-based cancer vaccines for immunotherapy." (PMID 34439192, 2021). "Here, we investigated the potential of the BacMam virus, a modified baculovirus for gene delivery into mammalian cells, as a novel multigene delivery system to generate a cell-based cancer vaccine secreting the self-assembling IL-15:IL-15Rα complex." (PMID 34439192, 2021). "Several viral vector-based systems including lentivirus and adenovirus have been used to deliver the IL-15 and/or IL-15Rα gene to cell-based cancer vaccines." (PMID 34439192, 2021). "These properties result in a reduced risk of toxicity related to cytokine spikes, making the IL-15:IL-15Rα complex the most favorable form for cancer immunotherapy in humans." (PMID 33671252, 2021). "Collectively, we demonstrate a vaccine platform consisting of BacMam virus-infected B16F10 or CT26 cancer cells that secrete IL-15:IL-15Rα." (PMID 34439192, 2021). "Immunization with BacMam-based IL-15:IL-15Rα-secreting cancer cells successfully raised memory immune responses against solid tumors in mice." (PMID 34439192, 2021). "In summary, the use of delivery systems such as vMyx-IL15Rα-tdTr, and related genetically modified viruses, has the potential to improve clinical outcomes of cancer therapy." (PMID 25329832, 2014). "This study is the first demonstration of a functionally competent soluble IL-15:IL-15Rα complex-related cancer vaccine using a baculovirus system and advocates that the BacMam system can be used as a secure and rapid method of producing a protective and therapeutic cancer vaccine." (PMID 34439192, 2021). "After infection with a BV, both the IL-15 and IL-15Rα proteins were well-expressed and could dimerize to form the biologically functional IL-15:IL-15Rα complex in either B16F10 or CT26 cancer cells." (PMID 34439192, 2021). "Therefore, we determined the working doses of the BacMam-based cancer vaccine for mice by conducting a dose–response study and the cell concentration that produced the optimum level of IL-15:IL-15Rα was selected for further experiments." (PMID 34439192, 2021). "Therefore, a more convenient technique for expressing exogenous IL-15 and IL-15Rα genes in cancer cells is needed." (PMID 34439192, 2021). "Moreover, IL-15 has also been complexed with IL-15Rα and this novel agent has been used as an immunotherapy in cancer patients in vivo." (PMID 30842774, 2019).
cancer (continued). "This study emphasizes the promise of using IL-15/IL-15Rα complex in cancer therapy and also implies that ALT-803 may improve the antitumor activity of TIL or CAR therapies in patients without increased toxic side effects." (PMID 30842774, 2019). "IL-15 trans-presentation is being explored for cancer immunotherapy; induction of constitutive expression of IL-15 and IL-15Rα by DCs or the use of soluble IL-15/IL-15Rα complexes has been shown to enhance NK cell antitumor activity in vitro and in preclinical mouse studies (reviewed in Ref." (PMID 29491009, 2018). "Activation of NK cells by cytokine trans-presentation has been mainly studied using IL-15;8, 33, 34, 35 IL-15 bound on an IL-15 receptor α chains (IL-15Rα of various cells such as activated monocytes, dendritic cells, and cancer cells have shown to enhance proliferation and cytotoxicity of NK cells." (PMID 28074895, 2017). "Thus, in this report we show that our novel IL-15/IL-15Rα designer DC are promising candidates to improve DC vaccination strategies in the battle against cancer, based on two different key points." (PMID 26675759, 2015). "To determine whether intracellular IL-15 also requires IL-15Rα to function, we used anti-IL-15 antibodies to immunoprecipitate cancer cell-intrinsic IL-15 and found that IL-15 was associated with IL-15Rα but not with the IL-2/IL-15Rβ or IL-2Rγ chains." (PMID 38637902, 2024). "In this study, we engineered a BacMam virus (BV) to carry either the self-assembling IL-15 or the IL-15Rα gene and evaluated whether immunization with a BacMam-based IL-15:IL-15Rα complex-expressing cell-based cancer vaccine could provide anticancer protection in mice." (PMID 34439192, 2021). "Since cancer cells in the tumors were exposed to interferon‐γ (IFN‐γ), we determined the expression of IL15Rα on 4T1 cells in the presence of different concentrations of IFN‐γ." (PMID 39625860, 2025). "The ability of IL-15 that is trans-presented by IL-15Rα to activate NK cells and CD8+ T cells has generated a lot of interest in exploiting it for cancer immunotherapy." (PMID 34956227, 2021). "We produced a fusion protein of mouse IL15Rα and the F8 antibody, that targets the alternatively-spliced extra-domain A (EDA) of fibronectin, which is overexpressed in many types of cancer." (PMID 31348785, 2019). "The IL-15 superagonist complex with IL-15Rα, named ALT-803, is being actively tested in the clinic for the treatment of cancer." (PMID 30072983, 2018). "Among the biomarker gene pairs, PPP1R13L, EGFR, IL15RA, or PIM1 are acting in the cancer core pathways." (PMID 26916442, 2016). "Our data showed that, unlike monomeric IL-15, the IL-15/IL-15Rα complex cannot antagonize the cancer cell-intrinsic IL-15-mediated promotion of cancer cell aggressiveness." (PMID 38637902, 2024). "This functional assay confirmed that the IL-15 and IL-15Rα coding genes delivered by BV were successfully expressed, and the proteins were self-assembled and functionally competent as a secreted form in the B16F10 and CT26 cancer cells." (PMID 34439192, 2021). "This targeting mechanism of ExoDS may be attributed to a variety of membrane receptors like integrin α and β chains (αMβ2), ICAM-1, MFG-E8, TNF, FasL, CD86, CD80, CD40, CD83, MHC-I, MHC-II, NKG2D, IL-15Rα, CD21, CD11c, and CCR7, which help mDC-derived exosomes identify cancer cells." (PMID 38903193, 2024). "Expression of other receptor molecules (IL13RA1, IL15RA, IL22RA1 and IFNGR1/2) was increased in carcinoma tissue, however due to our FC restriction we did not test these mRNAs for associations with miRNA differential expression." (PMID 30603058, 2018).
infection (18 papers, 2010 to 2026). The state of being infected such as from the introduction of a foreign agent such as serum, vaccine, antigenic substance or organism. "We show that IL-15-deficient mice succumb to infection whereas IL-15Rα-deficient mice clear the pathogen as efficiently as wildtype mice." (PMID 34956227, 2021). "However, the systemic immune-protective mechanisms of fish IL15Rα during a pathogenic infection are still unclear." (PMID 38066992, 2023). "After V. harveyi infection, Ec-IL15Rα in head kidney, spleen and gill were significantly up-regulated and up to top at 6 h post-infection." (PMID 38066992, 2023). "After infection with Edwardsiella tarda and Streptococcus iniae, Rb-IL15Ra of Oplegnathus fasciatus increased in the trunk kidney, head kidney and spleens." (PMID 38066992, 2023). "The mRNA levels of Ec-IL15Rα were obviously positively regulated and maximized at 6 h post-infection in gill, spleen and head kidney, at 12 h in the liver, heart, brain and muscles, at 48 h in thymus, and at 72 h in the intestines." (PMID 38066992, 2023). "WT and Il15ra-/- mice received neutralizing anti-IFNγ antibody 18 hours before infection and at 1 dpi and were sacrificed at 3 dpi." (PMID 34956227, 2021). "Reconstitution of Il15-/- mice with WT or Il15ra-/- BM was sufficient to control the bacterial load, and Il15ra-/- mice harboring Il15-/- BM cells still controlled the infection." (PMID 34956227, 2021). "Even though several studies have established a role for IL-15 in conferring protection against infections, few have addressed the role of IL-15Rα in pathogen control." (PMID 34956227, 2021). "Fusion proteins IL-15GFP and IL-15RαGFP were also constructed to analyze the BV infection and the expression of IL-15, IL-15Rα, or the IL-15:IL-15Rα complex at the single-cell level." (PMID 34439192, 2021). "Among these, some became upregulated during the early stage of infection (day 4) CCL7, CXCL11, IL1R1 (cytokine receptor) and IL15RA, and others became upregulated during the late stage of infection (day 7): IL2RA, CSF2RB and others." (PMID 27595844, 2016). "Strikingly, HTNV-infection was found to up-regulate the expression of IL-15 and IL-15Rα mRNA in both endothelial and epithelial cells." (PMID 25412359, 2014). "A two-fold increase in IL-15 and ten-fold increase in IL-15Rα mRNA levels were observed 24 h and 48 h, respectively, after HTNV-infection, and IL-15 and IL-15Rα mRNA levels remained at elevated levels until at least 96 h post infection." (PMID 25412359, 2014). "In vitro testing of the virus showed that B16-F10 cells are permissive to the vMyx-IL15Rα-tdTr infection." (PMID 25329832, 2014). "IL15RA was identified as a potential marker for genetic resistance to infection in cattle." (PMID 41144480, 2025). "In contrast, our observations here indicate that NK cell-intrinsic deficiencies for Stat3, Il15ra, or Il10r1 do not impact systemic IFNγ production or Lm bacterial burdens at 24 h post-infection." (PMID 31552035, 2019). "In contrast, 9 out of 11 IL-15Rα−/− mice died within 18 days after infection." (PMID 20300179, 2010). "At 24 h after infection with L. infantum, we observed a 2- to 2.5-fold increase of the percentage of IL-15Rα+ mDC in the spleen, indicating that L. infantum might modulate the IL-15/IL-15R system." (PMID 20213736, 2010). "However, it remains to be seen if or how deletion of Stat3, Il15ra, or Il10r1 in these other populations might impact resistance to other infections or otherwise alter inflammatory and immune responses." (PMID 31552035, 2019). "IL15 or IL15/IL15Rα complex induces robust proliferation of NK cells, NK T cells, memory CD8+ T cells, etc., promoting immune response and anti-infection." (PMID 38066992, 2023). "Suggesting that Ec-IL15Rα may play roles in enhancing the binding and assisting Ec-IL15, to co-express and operate together against pathogen infection." (PMID 38066992, 2023).
infection (continued). "We observed 80% survival in WT GMP‐transplanted mice after infection but no survival of IL15RA‐KO GMP‐transplanted mice (50,000 GMPs for each genotype), demonstrating that IL‐15 signaling from myeloid cells was required for NK cell support." (PMID 37635627, 2023). "However, they did not determine the effect of IL-15/IL-15Rα in the frequency of the different NK cell maturation subsets as determined by CD27 and CD11b expression or the NK cell protective function during a pathogenic infection." (PMID 25399821, 2015). "For the analysis of the IL-15 BV or IL-15 BV + IL-15Rα BV infection in the absence of GFP, the secreted IL-15 protein or the complex were quantitated by IL-15 monomer-specific or IL-15:IL-15Rα complex-specific ELISA kits." (PMID 34439192, 2021). "As increased production of soluble mIL-15/IL-15Rα complex also correlated with increased MOI, together these data indicate that production of soluble mIL-15/IL-15Rα complex is dependent on initial gene dosage at infection but does not require viral replication for continued production." (PMID 24312353, 2013).
bacterial infection (3 papers, 2021 to 2024). "Clearly, further studies are needed to identify the cell type involved in IL-15-dependent IL-15Rα-independent early IFNγ production following bacterial infection." (PMID 34956227, 2021). "Although different expression patterns were detected in different fish, IL15Rα was widely distributed and could certainly be induced by bacterial infection to play roles in immune defense." (PMID 38066992, 2023). "As BMDMs are diverse in their phenotype, it raised the possibility that lack of IL-15 signaling, in the presence or absence of IL-15Rα, might impact the frequencies of BMDM subsets with altered susceptibility to bacterial infection." (PMID 34956227, 2021). "The dispensability of IL-15Rα but not IL-15 to clear low dose L. monocytogenes infection indicated that IL-15 signaling can occur independently of IL-15Rα and that this signaling plays a key role in the control of bacterial infections." (PMID 34956227, 2021).
cardiovascular disease (2 papers, 2021 to 2024). "IL-15RA mediates pleiotropic proinflammatory signals involved in several inflammatory and cardiovascular disorders." (PMID 38919625, 2024).
psychiatric disorder (1 paper, 2022). A disorder characterized by behavioral and/or psychological abnormalities, often accompanied by physical symptoms. "When combined with our previous results from animal experiments, this study provided clinical evidence of the role of IL-15Rα in psychiatric diseases." (PMID 35356722, 2022).
IL15RA also shares sentences with these, for which no sentence is quoted: ovarian carcinoma (3 papers); renal disease (3); celiac disease (2); colorectal cancer (2); non-small cell lung carcinoma (2); Stroke (2); acute lymphoblastic leukemia (1); age (1); allergic asthma (1); atopic dermatitis (1); brain tumor (1); bronchitis (1); colitis (1); coronary artery diseases (1); end-stage renal disease (1); hepatocellular carcinoma (1); HIV-1 infection (1); Hyperglycemia (1); intestinal disease (1); iridocyclitis (1); lung carcinoma (1); lung fibrosis (1); lupus (1); lymphoproliferative disorder (1); memory impairment (1); meningitis (1); myotonic dystrophy type 1 (1); neuroblastoma (1); neurological diseases (1); renal fibrosis (1).
A further 10 diseases each share a sentence with IL15RA in 1 paper.